CD44 (CD44 molecule (IN blood group))
Diseases named in the same sentence as CD44 in open-access papers (continued):
Sharing a sentence is not in itself a finding about the gene and the disease.
cancer (continued). "To this aim, we first employed a set of antibodies directed against surface (cancer) stem cell markers and adhesion molecules in combination with EpCAM and CD44." (PMID 39246444, 2024). "Nine clusters within cancer cells were identified, including breast cancer stem cells (BCSCs), denoted as CD44, ALDH2, and ALDH6A1 + cells." (PMID 38064127, 2024). "Our data indicated that 86.1% of the mesenchymal type MDA-MB-231 cancer cells showed the CD44+/CD24− immunophenotype representative of the subpopulations of CSCs." (PMID 38392969, 2024). "All the evidence shows that CD44 plays an important role in cancer treatments by nanoparticles modified by CS and other drugs." (PMID 38783892, 2024). "We also found that CD44, a major cancer stem cell marker, was highly expressed in the cultured spheroids." (PMID 38890730, 2024). "Here we review published evidence on the potential utility of these protein families and in particular of CD44 as potential cancer therapeutic targets." (PMID 38761292, 2024). "This scoping review systematically examined the relationship between CD44 expression and chemotherapy treatment outcomes across a diverse range of cancers." (PMID 38542115, 2024). "HA/CD44 promotes cancer cell survival and motility via AKT activation, which is in line with our previous findings showing decreased expression of phosphorylated AKT with poor motility in tendinopathic tenocytes by blocking CD44 with an antagonizing antibody." (PMID 38309291, 2024). "While many in vitro and animal studies have shown that CD44 confers chemoresistance, the relationship between CD44 and chemotherapy treatment outcomes in cancer patients is ambiguous." (PMID 38542115, 2024). "The C2-E.T cluster exhibited concurrent high expression of POU5F1 and CD44, recognized markers of cancer stem cells (CSCs), indicating the presence of CSCs attributes in the C2-E.T cluster." (PMID 38191424, 2024). "The majority of GD2+ cells are also CD44 and CD24 positive and previously considered to associate with cancer stem cell surface phenotypes." (PMID 38731901, 2024). "These compounds have all shown promise in reducing the CD44+ CSC population in different cancer cell lines." (PMID 38672650, 2024). "CD44 plays an important role in the prolactin-driven accumulation of labile iron pools inside cancer cells." (PMID 39201626, 2024). "Here we showed reduced mRNA and protein levels in the cancer stemness markers Sox2 and CD44 in the organoids following Metavert treatment." (PMID 39217851, 2024). "Taken together, these interactions promote EMT and CD44-induced metastasis resulting in enhanced treatment resistance capacity and poor prognosis in cancer patients." (PMID 38816670, 2024). "Numerous studies over the past two decades have shown that CD44 is important in cancer cell identification, behavior, and as a prognostic factor in patients." (PMID 38539529, 2024). "Among them, the high expression of CD200 is related to the immune escape and poor prognosis of malignant tumors, and the regulatory role of CD44 in cancer stem cells of HNSCC patients has been clarified in recent researches." (PMID 38347320, 2024). "Studies have also shown that overexpression of CD44 promotes disease progression by enhancing chemoresistance and anti-apoptotic programs in cancer cells." (PMID 38539529, 2024). "Previous studies indicated the significance of CD44 in sustaining cancer stem cells (CSCs) and its role in governing oxidative stress levels in human HCC cell lines, such as Huh7." (PMID 39055490, 2024). "Targeting CD44, including neutralizing antibodies or pharmacological inhibitors, is being studied in preclinical and clinical trials for cancer therapy." (PMID 38264936, 2024). "UC2288 and SGC-CBP30 reduced ALDH and CD44 levels, and the proportion of cancer stem-like cells in all four cell lines." (PMID 38553760, 2024).
cancer (continued). "In a study of 38 patients, including 13 with benign tumors, CD44 and CD44v6 isoforms were found to be upregulated in benign tumors compared to the control group, though their levels were slightly lower than in malignant tumors." (PMID 39684268, 2024). "Because chemokines have important effects on immune cell migration into cancers, we investigated the effect of CD44 on chemokines and chemokine receptors." (PMID 38590654, 2024). "Although animal experiments supported the effect of hyaluronic acid (HA)-modified liposomes on the delivery of chemotherapeutic agents to cancer cells with high CD44 expression, research on targeted therapy and immunotherapy is lacking." (PMID 38462618, 2024). "In cancer proliferation hyaluronic acid, the main component of the cellular matrix, attach to the CD44 marker on cancer cells triggering several biological activities." (PMID 39026213, 2024). "These modified EVs efficiently deliver chemotherapeutic drugs to drug-resistant cancer cells through CD44-mediated targeting." (PMID 39513123, 2024). "A cancer stem cell (CSC) sub-cluster was selected among 12 cancer cell sub-clusters due to an enrichment in stem cell marker expression, such as CD44, CD98, CD47, and CD276." (PMID 39409886, 2024). "In contrast to normal cells, numerous cancer cells, such as those from lung, breast, pancreatic, gastric, and colon tumors, have heightened expression of CD44, representative its potential as a potential target for cancer therapy." (PMID 39598555, 2024). "HA-based drug delivery systems have shown promise in cancer treatment due to the high affinity between CD44-overexpressed receptors and HA." (PMID 38675202, 2024). "The present study comprehensively explored the significance of CD44 in predicting prognosis of cancers as well as its effect on the immune microenvironment." (PMID 38590654, 2024). "CD44 promotes activation of MAPK, p38, and so on, which is associated with cancer cell stemness, growth, radiation resistance, and cell proliferation." (PMID 38783892, 2024). "It was shown in the literature that cancer cells expressing higher levels of CD44 are more resistant to apoptosis." (PMID 38790277, 2024). "The relation of CD44 with 14 functional states within pan-cancer was analyzed based on CancerSEA database." (PMID 38590654, 2024). "Comparison of the expression differences of CD44 among different cell clusters in the six cancer types demonstrated that CD44 had the highest expression in mast cells of KIRC, STAD, HNSC and CRC." (PMID 38590654, 2024). "Salinomycin was shown to be an effective ferroptosis inducer in mesenchymal state cancer cells that have a high expression of the plasticity marker CD44." (PMID 38908072, 2024). "Spearman’s correlation analysis revealed that CD44 was correlated with 14 major immune checkpoints and co-stimulating factors within diverse cancer types." (PMID 38590654, 2024). "Twist is mainly related to EMT in cancer cells, and CD44 is found to play a key part in the adaptive plasticity of cancer cells by regulating Twist signaling." (PMID 38783892, 2024). "Among the CD44 isoforms, CD44v6 has been shown to play a major role in cancer progression due in part to its ability to directly bind to major cytokines produced in the TME." (PMID 39766174, 2024). "Given the clinical and pathological impact of CD44, it represents a promising molecular target for cancer therapy." (PMID 38672650, 2024). "We evaluated the mRNA levels of typical cancer stem markers, CD44, LGR5, SOX2, and TROY, using qRT-PCR." (PMID 38669046, 2024). "In 2016, Umemura and Ihkoshi showed that overexpression of CD44 on cancer cells induces resistance via enhanced DNA repair." (PMID 39791719, 2024). "Of note, EVAML were highly enriched in cancer stem cell markers, namely, CD44 (p < 0.0001) and CD133-1 (p = 0.009), in comparison to EVHD." (PMID 39738118, 2024).
cancer (continued). "The results indicated that CD44 exhibited significant heterogeneity in infiltrating degrees of immune cells within diverse cancer types." (PMID 38590654, 2024). "CD44 is a known poor prognostic factor expressed in cancer cells, promoting the invasion and metastasis of cancer cells through hyaluronic acid." (PMID 39758992, 2024). "We conducted a systematic analysis of the expression profile and genomic alteration profile of CD44 in 33 types of cancer." (PMID 38590654, 2024). "Various variants of the CD44 protein have been detected within exosomes released from mesenchymal stromal cells and cancer cells, and CD44-positive exosomes have been found in body fluids." (PMID 39872532, 2024). "In this review, we have mainly discussed the influence of CD44 expressing in cancer cells and therapeutic strategies through targeting CD44." (PMID 38783892, 2024). "CD44+/ALDHHigh cancer cells were shown to exhibit activated vimentin, correlating with enhanced cell plasticity and tumorigenicity." (PMID 39768151, 2024). "Natural compounds and chemotherapeutic agents can indirectly inhibit CD44 isoforms overexpressed in cancer cells and CSCs." (PMID 38672650, 2024). "Targeting CD44 isoforms can potentially reverse malignant behavior and increase cancer cell sensitivity to therapy." (PMID 38672650, 2024). "Simultaneously, the delivery of the mentioned particles (miR and siPD-L1) will downgrade expression in both PD-L1 and CD44 and increase apoptosis through the sensitisation of cancer cells." (PMID 39408718, 2024). "CD44 and its isoforms have potential prognostic and predictive roles in cancer treatment response, making them potential targets for anticancer therapies." (PMID 38672650, 2024). "To further validate the efficacy of ML-SI1 in eradicating cancer stem cells, we also utilized CD44+/CD24− as an additional marker for identifying these cells." (PMID 38802335, 2024). "We aimed to assess the tumorigenic biomarkers soluble CD44 (solCD44) and total protein (TP) measured using oral rinses as affordable convenient screening tools for cancer detection." (PMID 39030509, 2024). "Apart from that, naïve exosomes can also suppress the invasiveness and the migration ability of BCCs, enhance their cell adhesion, and reversibly restrain their CD44 (cancer stem cell marker) level." (PMID 39000239, 2024). "To elucidate the role of CD44 in the adhesion between ECs and cancer cells, we introduced an anti-CD44 antibody into the medium of the ECs and seeded them with LLC-GFP after 1 h." (PMID 39758992, 2024). "SPP1 binds to various receptors, including CD44 which has been recognized as an essential cell surface marker of cancer stem cells, driving treatment resistance and poor prognosis in various tumors." (PMID 38491408, 2024). "CD44 also regulates glucose metabolism in various cancer cells (such as PC-3 cell line and small cell neuroendocrine carcinoma cells), while also modulating ROS levels and cellular proliferation within neoplastic cells." (PMID 38736891, 2024). "As introduced in Results, these findings fit with reports of GPNMB/CD44 signaling in mesenchymal, neural, and cancer cells." (PMID 39052353, 2024). "CD44 expression is increased in cancer cells undergoing EMT and those cancerous cells with acquired stem-like properties." (PMID 38791985, 2024). "A number of studies have also highlighted the effect of CD44 on AKT in relation to cancer cell growth, motility, invasion and stemness." (PMID 38783892, 2024). "Token together, little research has been done on CAR T cells targeting CD44 expressing cancers cells, but it is being rolled out and is a novel therapeutic strategy." (PMID 38783892, 2024). "As a result, utilizing a hydrophilic HA layer on liposomes provides them with physiological stability and imparts active targeting potential to liposomal nanocarriers, facilitating their internalization into cancer cells through HA/CD44 interactions." (PMID 39055490, 2024).
cancer (continued). "Only a small proportion of CD44 isoform-expressing cancer cells was also positive for the Ki-67 proliferation marker (Supplementary_Figure_2a)." (PMID 38600583, 2024). "Overall, these data suggest that pharmacological therapy that suppresses CD44 expressing in cancer cells is a promising strategy." (PMID 38783892, 2024). "First, since CD44 is found on the surface of cancer cells, it is more accessible to the therapeutic agents which block its ability to carry out its negative functions." (PMID 38539529, 2024). "Hyaluronic acid-coated bovine MEs was able to specifically target CD44-positive cancer cells and significantly increased antitumor efficacy without systemic toxicity." (PMID 38951872, 2024). "In summary, CD44 appears to be an attractive molecular target for the modulation of several signaling pathways that drive important biological processes in cancer." (PMID 38761292, 2024). "To date, CD44 has been extensively studied in the field of cancer biology and has been proposed as a marker for cancer stem cells." (PMID 38731968, 2024). "Endothelial marker CD31 indicates an intact endothelium lining essential for barrier function, while CD44 indicates the model’s malignant potential, mimicking the complexities of the cancer microenvironment." (PMID 38786516, 2024). "CD44 is a cell surface adhesion molecule overexpressed on cancer stem cells, thus applied in surface modification of Doxorubicin (DOX) loaded EVs for cancer therapy." (PMID 39567444, 2024). "Further research is needed to examine the effects of CD44 expression across a wider variety of cancer types and chemotherapy drugs to achieve a more comprehensive understanding of the role of CD44 in cancer treatment outcomes." (PMID 38542115, 2024). "OSCC harbors a subpopulation of CD44(+) cells that exhibit cancer stem-like cell (CSC) characteristics are involved in malignant tumor phenotype and radioresistance." (PMID 38355684, 2024). "CD44 is a cell surface glycoprotein highly expressed on normal stromal cells and on stem cells, in the vast majority of cancers." (PMID 39840036, 2024). "The decrease in activated c-MET and CD44 levels following Gal-4 knockout indicates that Gal-4 plays a significant role in activating these pathways, promoting cancer cell proliferation and metastasis." (PMID 39664377, 2024). "Cancer stem cells (CSCs) isolated from HCC are characterized by the expression of stem cell markers CD44, CD133 and alpha‐fetoprotein (AFP), and inhibition of these markers has been regarded as a reliable indicator for response to chemotherapy." (PMID 38722284, 2024). "The interaction between CD44 and its ligands plays a vital role in the development of cancer, affecting important cellular processes like adhesion, motility, growth, and survival of cells." (PMID 38544254, 2024). "A separate investigation on cancer stem-like cells (CD24−/CD44+/ESA+) showed that resveratrol controls FAS expression, hinders lipogenesis, and triggers death in these cells." (PMID 39204369, 2024). "Only two transcriptomic signatures reported were composed of co-expressed genes: the cancer stem cell markers CD44, CD24, and ESA; and TSPAN8 and SOX9." (PMID 39200223, 2024). "A recent study has found that in cancer cell lines, through the endocytosis of iron‐bound HA regulated by CD44, the EMT was enhanced." (PMID 38783892, 2024). "On the other hand, the expression level of cancer stem cell marker CD44, which was overexpressed in M-EPIR (epirubicin-resistant MCF-7 subline) compared to MCF-7, was significantly suppressed by knockdown of RHAMM." (PMID 39518040, 2024).
cancer (continued). "Quantitative polymerase chain reaction (qPCR) revealed that the transcription level of MIR31HG, as well as three stem cell specific markers (CD133, CD34, and CD44) were significantly higher in cancer stem cell types than in parental cells." (PMID 37950038, 2024). "Taken together, in addition to the discovery of the direct effect of PTX3 on cancer cells and macrophages, recent evidence potentially supports an effect of CD44 and PTX3 on regulating Treg activation or differentiation." (PMID 38243273, 2024). "Currently, most studies have indicated that a high CD44 level predicts a poor prognosis for cancer patients, but some studies have reported opposite results." (PMID 38590654, 2024). "Multiple studies have emphasized the carcinogenic features of CD44, establishing it as a crucial cancer biomarker." (PMID 38544254, 2024). "In most cancers, CD44 was positively correlated with chemokines of the CXC subfamily, while CD44 was negatively correlated with most chemokines in ESCA." (PMID 38590654, 2024). "This enhanced efficacy and prolonged retention make the α-MG-loaded NP conjugated to the CD44 thioaptamer a promising candidate for further exploration in cancer therapy." (PMID 38675202, 2024). "Recently, CD44 isoforms have been found as an promising target for chimeric antigen receptor T cells (CAR T cells) to eliminate CD44 expressing cancer, which is a novel and specific treatment." (PMID 38783892, 2024). "We observed a significant increase in the expression of cancer stem cell markers, including CD44, VEGFA, ITGB1, ALDH1A3, SOX9 and NECTIN4, and enrichment in stemness-related pathways, such as the hedgehog, PI3K-AKT-mTOR, and WNT signaling pathways." (PMID 38892065, 2024). "Recent studies have established the relationship between CD44-positive exosomes and cancer progression." (PMID 39273689, 2024). "Encapsulated glycosylated paclitaxel liposomes (gPTX-L) conjugated with anti-CD44 antibodies enhance cytotoxicity efficiently in vitro and in vivo in human ovarian overexpressed CD44 cancer cell lines." (PMID 38672650, 2024). "CD44 is a cell surface glycoprotein that plays a critical role in cell adhesion, cell migration, and cancer cell invasion." (PMID 38612715, 2024). "Encapsulating doxorubicin (DOX) in HA-targeted liposomes was highly effective in killing cancer cells expressing high levels of CD44." (PMID 38672650, 2024). "In our study, we coated the surface of the nanohybrid system with HA, which is a well‐known ligand for CD44 overexpressed in many types of cancer stem cells." (PMID 39279556, 2024). "Following the administration of 55, the levels of stem cell factors Oct4, Sox2, Nanog, and CD44 were notably reduced, indicating its potential effectiveness as a therapeutic agent against cancer." (PMID 39204369, 2024). "The resistant cells had a significantly greater CD44+/CD24- subpopulation than the parental cancer cells." (PMID 38737455, 2024). "While CD44 is an indispensable marker for CSC selection in other cancers like breast or colorectal cancer, this study found that OCT4, SOX2, and NANOG were more suitable for identifying CSCs in HNSCC." (PMID 39409886, 2024). "In vitro studies demonstrated significant entry of most NPs into cancer cells through the interaction of HA in NPs with CD44 in cancer cells, with the presence of the TAT peptide facilitating cellular uptake." (PMID 39065565, 2024). "CD44 expression on cancer cells was shown to be up-regulated through rhIL-1β treatment, suggesting a positive feedback loop to maintain IL-1β levels." (PMID 39044824, 2024). "VTD effectively targets sorted CD44 + and LgR5 + positive stem cells, which strictly defines cancer stem cells in CRC." (PMID 39502780, 2024). "The results clearly demonstrated that the reduction of CD44 expression in vascular ECs significantly diminishes the ability of cancer cells to adhere." (PMID 39758992, 2024).